NANOG (Nanog homeobox)
Diseases named in the same sentence as NANOG in open-access papers (continued):
Sharing a sentence is not in itself a finding about the gene and the disease.
tumor (continued). "We analyzed for the first time the relative mRNA expression for OCT4, SOX2, KLF4, C-MYC, and NANOG in tumor and normal cells." (PMID 31885625, 2019). "Consistent with the in vitro findings, NANOG knockdown abolished the tumor-enhancing effect of IL-6." (PMID 30804456, 2019). "No other significant correlations were observed in our series between NANOG expression with known prognostic factors, such as clinical stage, tumor size or neck lymph node metastasis." (PMID 31484317, 2019). "The present results with NANEP5 therefore raise the possibility that the activating function of NANOG is critical for its role in tumor stemness and growth." (PMID 30846719, 2019). "Alu induction and NANOG repression was weaker than in PC-3 cells, perhaps because the tumour biopsies included untransformed contaminating cells." (PMID 30820548, 2019). "It has been reported that CD24 regulates NANOG expression through STAT3 phosphorylation and that pSTAT3 (Y705) bound to the NANOG promoter drives tumor onset and self-renewal in the liver." (PMID 30804456, 2019). "Primordial germ cells preserve so their undifferentiated state, as demonstrated by the expression of a lot of stem cell markers, including OCT4, NANOG, stage-specific embryonic antigens and tumor rejection antigens." (PMID 31572301, 2019). "In order to determine the mechanism of QYHJ on GEM resistant tumor tissue, we detected the mRNA expression of lncRNA AB209630, miR-373, EphB2, and NANOG in tumor tissue." (PMID 31147453, 2019). "Several lines of evidence have suggested that expression of OCT4 and NANOG is closely related to tumorigenesis, distant recurrence, and tumor metastasis after treatment." (PMID 30082842, 2018). "Destroying NANOG in activated MSCs in the tumor bed by the immune system will limit the immune inhibitors and is an added advantage." (PMID 29971070, 2018). "Accumulating evidence also indicates that the activation of endogenous interconnected auto-regulatory loops formed by OCT4, SOX2, and NANOG is important for tumor oncogenesis." (PMID 30510261, 2018). "The stem cell factors SOX2, OCT4, and NANOG form positive feedback loops to maintain stemness in ESCs, and their involvement in tumor malignancies has been reported in several cancers." (PMID 30510261, 2018). "CD133 has crucial roles in tumor cell proliferation, colony formation, and the expression of stemness genes, including NANOG, OCT4, SOX2, and c-MYC." (PMID 30671168, 2018). "Analysis of TMA-based immunohistochemistry staining demonstrated that expression of OCT4 and NANOG was localized to the nucleus and cytoplasm of the tumor cells." (PMID 30082842, 2018). "NANOG inhibiting compounds like RNAi or small inhibitors, therefore, have to be given lifelong to keep the tumor encaged." (PMID 29971070, 2018). "The expression levels of these three molecules (CD24, CD49f, and NANOG) in primary tumour tissues were significantly higher in subjects with positive expression in urine samples than in those with negative urine expression." (PMID 30327565, 2018). "DIDO1 can exert its tumor suppressor role through apoptosis induction and its oncogenic role via the activation of NANOG." (PMID 30157793, 2018). "NANOG has been shown to be upregulated in different types of cancers and plays a role in tumor transformation, tumorigenicity, and metastasis within OCSCC." (PMID 28626726, 2017). "NANOG has previously been shown to be involved in tumor progression and castration resistance by binding to the androgen receptor/FoxA1 signaling complex." (PMID 29156833, 2017). "CUR was determined to reduce the expression of DCLK1/CD44/ALDHA1/LGR5/NANOG in CRC CSC three-dimensional spheroid cultures as well as in tumor xenografts." (PMID 28611316, 2017). "It will be interesting in the future to examine the correlation of CD44v6 and NANOG in tumor invasion and progression of PCa tumors." (PMID 29156833, 2017).
tumor (continued). "IF IHC staining showed the presence of a SOX2+/NANOG+/KLF4+/c-Myc+/OCT− CSC subpopulation within the tumor nests, and a SOX2+/NANOG+/KLF4+/c-Myc+/OCT4− CSC subpopulation and a SOX2+/NANOG+/KLF4+/c-Myc+/OCT4+ CSC subpopulation within the peritumoral stroma." (PMID 29404335, 2017). "Because in vivo SORE6-GFP positive v6A3 cells still maintained the transcriptional activities of the NANOG promoter even in the complex tumor microenvironment, these cell populations are more likely to be CSC-like and/or aggressive PCa cells." (PMID 29156833, 2017). "NANOG knockdown significantly inhibited LAPC4 AI tumor regeneration and the inhibitory effect was particularly strong with TRC vector." (PMID 27867534, 2016). "NANOG was expressed by cells within the tumor nests (red) and the stroma (red), as well as the endothelium of the microvessels that stained positively for CD34 (green)." (PMID 27532037, 2016). "Nuclear staining for OCT4 (brown) and pSTAT3 (brown) of the cells within the tumor nests was noted, while primarily cytoplasmic staining with some nuclear positivity for NANOG (brown) was observed." (PMID 27532037, 2016). "The detection of a EMA+/CD44+/SOX2+/OCT4+/SALL4+/pSTAT3+/NANOG+ subpopulation within the tumor nests aligns with recent literature reporting localization of CSC in OCSCC, particularly at the “tumor front”." (PMID 27532037, 2016). "Protein levels of ZEB2, BMI1, OCT4, and NANOG were decreased in tumor spheres compared to parental NPC cells." (PMID 27589832, 2016). "DCLK1 knockdown resulted in decreased expression of OCT4 (>30%), KLF4 (>45%), LIN28 (>40%), and NANOG (>50%) in tumor xenografts." (PMID 26468984, 2015). "These EWS CSCs expressed putative pluripotency transcripts (i.e., OCT4 and NANOG), exhibited tumor initiating activity in vivo, and possessed a chemotherapy-resistant phenotype." (PMID 25806369, 2015). "NANOG protein, a transcription factor expressed in embryonic stem cells, is overexpressed in tumor development." (PMID 24348816, 2014). "Well-differentiated OSCC consists of numerous differentiated cells in the central region of the tumor and the majority undifferentiated tumor cells expressing NANOG exist at the fringe of focus." (PMID 24348816, 2014). "A systematic study using animal models and in vitro cell systems has provided substantial evidence for the key function of NANOG in human tumor development." (PMID 25120646, 2014). "As an example, the synergistic regulation of histone deacetylase 1 (HDAC1) by OCT4, SOX2 and NANOG plays important roles not only in the development of ESCs but also in the growth of tumor cells." (PMID 25171496, 2014). "Whereas NANOG disruption in ES cells results in differentiation to endoderm lineages, knockdown leads to inhibition of tumor development." (PMID 23969837, 2013). "Strikingly, 73% of non-tumor cases (11 out of 15) were more than 50% methylated, whereas 53% of tumor cases (8 out of 15) were less than 30% methylated at the NANOG promoter." (PMID 24023739, 2013). "In accordance with the reduced promoter methylation, NANOG expression was found significantly higher in tumor tissue than in non-tumor tissue (p = 0.021)." (PMID 24023739, 2013). "After stimulation with various concentrations of BCE (62.5, 125, 250, 500 or 1,000 μg/ml) for 24 and 72 h, tumor cells were analyzed by qRT-PCR or western blot analyses for the expression of the stem cell genes NANOG, POU5F1 and SOX2, respectively." (PMID 23969837, 2013). "Immunohistochemical analysis of tumor xengrafts further confirmed that treatment with ugonin J suppressed NANOG expression." (PMID 23662114, 2013). "A combined genomic analysis of the Oct-4/SOX2/NANOG pathway has recently demonstrated high prognostic accuracy in studies of patients with multiple tumor types." (PMID 22300949, 2012). "NANOG expression negatively correlated with tumor size (r = −0.383, p = 0.015)." (PMID 41596471, 2026).
tumor (continued). "Given that SPOP functions as a tumor suppressor and regulates NANOG degradation, restoring or mimicking SPOP activity could prevent NANOG accumulation and its subsequent oncogenic effects, including enhanced proliferation and metastasis." (PMID 40521202, 2025). "Circulating tumor cells warrant assessment as non-invasive biomarkers for NR5A2/NANOG expression." (PMID 41214698, 2025). "In some cases, NANOG expression was also detected in these pluripotent cells in the tumor mass." (PMID 40806546, 2025). "The key genes for CSCs to maintain stemness, such as OCT4, SOX2, and NANOG, were also significantly decreased after the combination treatment, further implying that the stemness of CSCs was reduced and different from that of normal tumor cells." (PMID 40785845, 2025). "It suppresses stemness traits of ESCC cells by targeting the deubiquitinating enzyme (USP8), diminishes the expression of stemness-related markers such as SOX2 and NANOG, decreases the sphere-forming capacity of drug-resistant cells, and lowers the incidence of tumor formation in vivo." (PMID 40710326, 2025). "Current investigations suggest that STAT3 and NANOG may have important roles at multiple stages of tumour progression." (PMID 40729003, 2025). "Secondary tumour foci consist of large quantities of actively proliferating CSCs, which may help to maintain high levels of NANOG." (PMID 40729003, 2025). "Therefore, NANOG, which promotes stem cell-like phenotype in tumor cells, is quantified using Real Time Polymerase Chain Reaction (RT-PCR) and analyzed." (PMID 40822502, 2025). "Moreover, P. gingivalis-enhanced expression of SOX2, BMI1, and NANOG in tumor tissues were remarkably reduced by SCD1 knockdown." (PMID 40016182, 2025). "It has been suggested by several studies that NANOG may have a role to play in the development of tumours." (PMID 40729003, 2025). "We enriched the CSC population through sphere culture from A549 and H1299 tumor-bearing mice and verified the enrichment using western blotting and flow cytometry to detect stem cell transcription factors (NANOG, OCT4, SOX2) and CSC surface markers (CD44, CD133)." (PMID 40093893, 2025). "Moreover, the patient-derived SPOP mutation Q360* impaired its nuclear localization, leading to NANOG accumulation in the nucleus, thereby driving tumor growth and metastasis." (PMID 40521202, 2025). "NANOG, SOX2, and OCT4 were found to be highly expressed in gastric cancer tumor tissues compared with those in adjacent healthy tissues, and their overexpression was associated with tumor size, tumor grade, and overall survival time." (PMID 40806148, 2025). "Blocking NANOG and consequently, NANOG-mediated regulatory circuits, which account for approximately 50% of malignancies, might be a possible strategy to prevent tumor initiation and progression." (PMID 38846985, 2024). "In addition, tumour samples were stratified according to NANOG expression according to tertiles (high (H), medium (M), low (L))." (PMID 38693576, 2024). "This is in line with NANOG’s influence on sphere creation and tumor aggressiveness in vivo." (PMID 39547513, 2024). "Moreover, studies suggest that NANOG possesses pro-tumorigenic attributes, which promotes tumor development and progression." (PMID 38233377, 2024). "NANOG has been shown to be involved in tumor recurrence and treatment resistance." (PMID 38561775, 2024). "In addition, HIF2α-specific targeted expression of known pluripotent factors, such as OCT4, SOX2, and NANOG, can affect stem cell function and promote tumor growth." (PMID 38243138, 2024).
tumor (continued). "AMBL was found to express ABCG2, ALDH1, BMI1, CD133, CD166, CD44, and c-Myc in peripheral and/or central cells of the parenchyma at variable extent and intensity levels, as well as CD34 in spindle-shaped stomal cells and LGR5 and NANOG in both epithelial and stromal tumor components." (PMID 37761874, 2023). "Here, we found that the TRPV1 is overexpressed by NANOG in cisplatin-resistant tumor cells and mediates Ca2+ influx and subsequent increases in autophagic EGF secretion, which activates the EGFR-AKT signaling pathway consequently contributing to cisplatin resistance." (PMID 37165076, 2023). "In addition, restoration of BACE1-AS in BACE1-AS knockout cells rescued tumor sphere formation capabilities and expression of NANOG, OCT4." (PMID 37986103, 2023). "TRRAP knockdown inhibited tumor growth and NANOG expression in the HCT-15 xenograft model." (PMID 37047234, 2023). "In addition, high levels of NANOG mRNA in PC tissue have been associated with high preoperative PSA levels, tumor volume, and lymph node metastasis." (PMID 37834336, 2023). "We postulate, that NANOG-positive tumors tend to have a higher tumor stage." (PMID 37461005, 2023). "Notably, the elevated level of TRPV1 mRNA in cisplatin-resistant tumor cells was repressed by NANOG knockdown, indicating the NANOG-dependent expression of TRPV1." (PMID 37165076, 2023). "To further investigate whether NANOG expression in tumor cells is responsible for the acquisition of cisplatin resistance by autophagy-mediated EGFR activation, we silenced the NANOG gene in cisplatin-resistant tumor cells using siRNAs." (PMID 37165076, 2023). "Recent data showed that NANOG could not only promote tumor initiation but also increase the formation of CSC colonies in HNSCC." (PMID 37626893, 2023). "The present study also brought evidence of NLRP7 involvement in the differentiation of tumor cells through the induction of embryonic markers such as NANOG, NOTCH1 and OCT3/4, and the activation of their survival through the induction of genes, such as CD74 and its co-receptor CXCR2." (PMID 36980199, 2023). "Additionally, another study elucidated a potential role of hypoxia-induced NANOG in tumor immunosuppression in melanoma via enhancement of TGF-β1 expression." (PMID 37614497, 2023). "Interestingly, NANOG knockdown reduced TRPV1 expression in those tumor cells, indicating that the NANOG axis was conserved in all tested cells." (PMID 37165076, 2023). "Notably, we found that NANOG knockdown reduced the resistance of cisplatin-resistant tumor cells to apoptotic cell death by cisplatin." (PMID 37165076, 2023). "Notably, IL20RB overexpression upregulated the mRNA levels of several tumor stemness markers, including NANOG, SOX2 and POU5F1, while IL20RB knockdown downregulated their mRNA levels." (PMID 38098005, 2023). "Further immunophenotyping studies using spheroid sections may be helpful in matching CAF and CIC identification with the expression of markers such as NANOG and SOX2, considering their confluent association with tumor prognosis." (PMID 37830632, 2023). "Previously, we reported that NANOG was a crucial transcription factor driving the multi-refractory phenotypes of tumor cells, such as stem-like, metastatic and anti-apoptotic properties and resistance to multi-modal therapies via autophagy-mediated hyperactivation of the EGFR-AKT pathway." (PMID 37165076, 2023). "To address this, we first silenced NANOG expression in cisplatin-resistant tumor cells." (PMID 37165076, 2023). "E2F1 is also high in qISC, where it might exert its known role as repressor of OXPHOS and mitochondrial function and promote FAO to support self-renewal and drug resistance via NANOG in tumor-initiating stem-like cells." (PMID 35448502, 2022). "Moreover, NANOG was also tumor site-specific and correlated with a favorable prognosis for pharyngeal tumors (rather than laryngeal)." (PMID 36497144, 2022).
tumor (continued). "Notably, we found that knockdown of NANOG significantly promoted the overall number of tumor-infiltrating CD8+ T cells (TILs) or tumor-reactive CD 8+ TILs in tumors treated with anti–PD-1." (PMID 35104240, 2022). "Notably, targeting of NANOG sensitized the immune-refractory tumor cells to trastuzumab-mediated CDC." (PMID 35606403, 2022). "However, IL6 was robustly induced only in the KDM5CHigh samples, and interestingly, it showed a significant positive correlation with NANOG only in this tumor subtype." (PMID 36142158, 2022). "Together, our results indicate that NANOG, as a tumor-intrinsic factor, could be a critical determinant that confers resistance to anti–PD-1 therapy by determining the immune feature of the TME." (PMID 35104240, 2022). "Interestingly, the expression of NANOG in apparently normal tissue around the tumor was higher than the normal proliferative endometrium, although it was not statistically significant." (PMID 35186145, 2022). "Based on these data, we conclude that NANOG is a critical mediator that could promote the CDC-refractory property in tumor cells encountering CTL-mediated immune selection." (PMID 35606403, 2022). "Clearly, both WB and IF showed that shRNA silencing CXCR4 synergistically enhanced the effect of PTX treatment on decreasing Akt phosphorylation and the resulting reduction in N-cadherin, vimentin, snail, CD44, CD133, and NANOG protein expression in OVCA420 tumor tissues." (PMID 35681259, 2022). "Analysis of LGR5 and NANOG expression levels by RT-PCR in these tumors revealed that in mice inoculated with tumor cells expressing PC inhibitors, the level of NANOG was reduced by up to 60% and 40% in Spn4A and α1-PDX-expressing cells injected mice, respectively." (PMID 35267511, 2022). "Pluripotency and reprogramming inducers OCT4 and NANOG, both repressed in an AhR-dependent manner during liver tumorigenesis and regeneration, were overexpressed in AhR-null livers in parallel with their enhanced senescence and tumor burden." (PMID 35619220, 2022). "This review article describes links between immunotherapies and microbiota in tumor-initiating stem-like cells (TICs), which have stem cell characteristics with self-renewal ability and express pluripotency transcription factors such as NANOG, SOX2, and OCT4." (PMID 35625986, 2022). "Significantly, AMP-depleted tumour-derived cells obtained after BT-474 injection into mice showed a reduction in NANOG, OCT4 and BMI1 gene expression, providing evidence that AMPK can also drive transcriptional upregulation and maintenance of stemness markers in the in vivo tumour microenvironment." (PMID 35195687, 2022). "Altogether, we propose that NANOG+ immune-refractory tumor cells enriched by immune selection drive the immune-refractory feature of the TME by simultaneously disrupting multiple steps of the antitumor immunity cycle, which provokes resistance to PD-1 blockade." (PMID 35104240, 2022). "Furthermore, MCL1 silencing reversed resistant phenotypes against the cognate CTLs of CT26-Nanog cells, suggesting a crucial role of MCL1 in the tumor-intrinsic CTL resistance induced by NANOG." (PMID 35104240, 2022). "Notably, inhibition of the NANOG/HDAC1 axis reversed the resistance to CTL-based immunotherapy in tumor cells and led to long-term control of the disease." (PMID 35104240, 2022). "Furthermore, we demonstrate that pharmacological inhibition of the NANOG/HDAC1 axis with FK228 triggered anti–PD-1 therapy–mediated tumor regression and made immunologically “cold” tumors “hot” by initiating or reinvigorating the antitumor immunity cycle." (PMID 35104240, 2022). "Together, these results indicate that NANOG expression in tumor cells could switch the immune phenotype of the TME from immune-stimulatory to immune-refractory feature by controlling both T cell infiltration into tumors and CTL-mediated killing of tumor cells." (PMID 35104240, 2022).